EGFR (epidermal growth factor receptor)
Diseases named in the same sentence as EGFR in open-access papers (continued):
Sharing a sentence is not in itself a finding about the gene and the disease.
breast carcinoma (continued). "Future therapeutic targeting of CD44v6 may prove to be an effective strategy alongside EGFR-targeted agents in delaying/preventing acquired resistance in breast cancer." (PMID 27379207, 2016). "Based on the premise that EGFR‐regulated lncRNAs might control the aggressiveness of basal‐like tumors, we identified multiple EGFR‐inducible lncRNAs in basal‐like normal cells and overlaid them with the transcriptomes of over 3,000 breast cancer patients." (PMID 27485121, 2016). "The finding that LIMT is downregulated in response to EGFR signaling and the ability of LIMT to inhibit metastasis in animal models correspond to our observations associating reduced LIMT expression with poor prognosis of breast cancer patients." (PMID 27485121, 2016). "A431 cells are breast carcinoma cells that express endogenous functional EGFR." (PMID 27559743, 2016). "In tamoxifen-resistant breast cancer cells, EGFR and ErbB3 recruit and phosphorylate IRS1." (PMID 27765041, 2016). "While the α,β-unsaturated-keto structure of EA is similar to that of irreversible TKIs, the mechanism of action of EA when combined with irreversible EGFR TKIs in breast cancer remains unknown." (PMID 27487128, 2016). "On the other way, EGFR signaling pathway could induce expression of insulin receptor substrate in breast cancer cells, which could stimulate IGF pathway." (PMID 27105537, 2016). "Ectopic expression of TLK2 leads to enhanced aggressiveness in breast cancer cells, which may involve the EGFR/SRC/FAK signalling." (PMID 27694828, 2016). "In addition, EVs can efficiently deliver another tumor-suppressive miRNA, let-7, to epidermal growth factor receptor (EGFR)-expressing breast cancer cells." (PMID 26861408, 2016). "It is well known that breast cancer is heterogeneous for EGFR, PR, and HER2 expression." (PMID 27050072, 2016). "Lapatinib, an EGFR/ErbB2 dual inhibitor, is used for advanced ErbB2-positive breast cancer cells." (PMID 26595522, 2016). "We also evaluated EGFR and AKT signaling, as HUNK has been previously implicated in both of these signaling pathways and the activity of those proteins are often deregulated in HER2-inhibitor resistant breast cancers." (PMID 27045589, 2016). "One example of high-level EGFR activity in the absence of mutation is the highly aggressive basal-like subtype of breast cancer (BLBC)." (PMID 27221039, 2016). "Among the different pathways associated with breast cancer BM formation, we will briefly discuss two stem cell pathways (Wnt and Notch) as well as the EGFR pathway (ERBB) because substantial evidence for the involvement of these pathways in BM has been obtained." (PMID 26781299, 2016). "PRLR and EGFR both have important roles in human breast cancer." (PMID 27564112, 2016). "MDA-MB-468 cells express high EGFR levels in comparison with most other breast cancer cell lines." (PMID 27495374, 2016). "Therefore, we conducted long-term treatments of human epidermal growth factor receptor-2 (Her2)-transformed breast cancer cells with either the EGFR/Her2 kinase inhibitor, Lapatinib or TGF-β, a known physiological inducer of EMT." (PMID 27825137, 2016). "Recent studies have shown that overexpression of EGFR is commonly found in breast cancer and is correlated with poor prognosis; thus, EGFR may be a potential therapeutic target." (PMID 27590506, 2016). "We began our study evaluating whether aldosterone could be able to activate the EGFR/ERK transduction signalling in SkBr3 breast cancer cells and B-TEC breast tumor-derived endothelial cells, which were used as model systems." (PMID 26646587, 2016). "CK5/6 and EGFR have been widely accepted as biomarker for basal-like breast cancer." (PMID 26930401, 2016). "In addition, resistance to tamoxifen in breast cancer cells has been related to overexpression of EGFR and high levels of phosphorylated extracellular activated kinase 1/2." (PMID 27494858, 2016).
breast carcinoma (continued). "In addition, crosstalk between BDKRB1 and EGFR has been shown to maintain tumor growth in the breast cancer." (PMID 27484806, 2016). "YB-1 is a transcription factor that binds to the EGFR promoter in breast cancer cells." (PMID 27713156, 2016). "Our results predict that MAPK pathway-activating mutations (such as KRASG12V) may be genetic mechanisms of resistance to HER2-direted therapy in indications outside of breast cancer, with higher EGFR and lower ERBB3 and CDKN1B expression." (PMID 27035903, 2016). "Taken together, these data suggest that EGFR/SRC/FAK axis may be important in TLK2-driven invasiveness in breast cancer cells, and TLK2 may engage this axis via interaction with SRC." (PMID 27694828, 2016). "The proteolytic activities of MMP-2 and MMP-9, expressed by macrophages, promote the release of cryptic fragments by cleaving laminin-5 γ2 chains which mimic EGF ligand and induce cell motility and invasion in EGFR overexpressing human breast carcinoma cell lines." (PMID 28053982, 2016). "It has found that the EGFR inhibitors erlotinib could prevent development of lung metastases in a spontaneous lung metastasis breast cancer mouse model." (PMID 27322074, 2016). "Further studies are needed to determine whether only mitochondrial-associated EGFR is subject to degradation by co-treatment with DCA and tamoxifen in breast cancer cells." (PMID 27494858, 2016). "While these observations, coupled with early pre-clinical studies of EGFR TKIs, suggested that EGFR would be a targetable in breast cancer, to date there has been minimal effect of TKIs in clinical trials, even when patient are stratified for EGFR overexpression." (PMID 27221039, 2016). "Therefore, to increase the efficiency of the clinical treatment, it is necessary to further explore the mechanism of EGFR-TKI response of breast cancer and assess multi-kinase inhibitors for combinational therapy, such as E1A gene therapy." (PMID 27590506, 2016). "Thus, the strategy of combining an EGFR inhibitor with an endocrine agent is of sufficient interest to warrant further study for breast cancer therapy." (PMID 27494858, 2016). "Anxa 2 is recently recognized to act as the downstreamer of EGFR signaling in breast cancer cells." (PMID 27274723, 2016). "A combination of EGFR-TKI with other treatments might be a useful strategy in breast cancer therapy." (PMID 27590506, 2016). "Collectively, these data suggest that Axl intrinsically activates an invasive/metastatic pathway in epithelial cells, consistent with previous reports that demonstrated the essential role of Axl in EMT transition in breast cancer metastasis and also in EGFR-targeted drug-resistant tumors." (PMID 27595981, 2016). "Data on EGFR amplification rates in breast carcinomas has been inconsistent ranging from 0.8-28%." (PMID 27602761, 2016). "Taken together, our studies have demonstrated essential role of ERα and STAT5b in EGF/EGFR induced activation of PRLR gene transcription/expression in breast cancer cells via STAT5b interaction with ERα and complex formation with Sp1/C/EBPβ at the PRLR promoter in the absence of estrogen." (PMID 27564112, 2016). "Consistent with a role for PDK1 in tumorigenesis, PDK1 overexpression and increased copy number in breast cancer has been shown to correlate with upstream lesions such as PTEN loss, PIK3CA mutation and EGFR amplification, and resulted in increased tumour growth, cell motility and poor prognosis." (PMID 27199173, 2016). "PD has been studied to possess inhibition potential on EGFR in human breast cancer cells." (PMID 27897231, 2016). "Other aptamers that can specifically bind to EGFRVIII, a frequently identified mutant form of EGFR in breast cancer, lung cancer and glioblastoma, were shown to possess great potential as molecular anti-tumor reagents in cancers carrying the EGFRVIII mutation especially glioblastoma." (PMID 26863567, 2016).
breast carcinoma (continued). "Taken together, these data all support the existence of a subgroup of ERα-positive breast cancers that become endocrine therapy resistant through activation of the EGFR signaling pathway, which may be mediated by a dynamic FOXA1 DNA binding landscape." (PMID 27129152, 2016). "This explicit hierarchical classification solution can identify the characteristic episodes in the EGFR endocytosis process and it has shown to be able to support the identification of new regulators in this crucial process relating to breast cancer progression." (PMID 27142862, 2016). "In other studies, ERBB2 had been reported as a significant biomarker of prognosis in other cancer types without EGFR-activating mutation such as breast cancer." (PMID 26824984, 2016). "Collectively, AXL may play a crucial role in resistance to EGFR inhibitors and may represent a critical therapeutic strategy for breast cancer." (PMID 27590506, 2016). "To investigate whether E1A would enhance the sensitization to EGFR-TKI in breast cancer cells, we examined the sensitivity to lapatinib, gefitinib or erlotinib in MDA-MB-231 and HBL100 cells with ectopic expression of E1A." (PMID 27590506, 2016). "Therefore, our observation on the role of δ-catenin in enhancing EGFR signaling in prostate cancer cells was consistent with the reported role of p120ctn on EGFR in breast cancer." (PMID 26883159, 2016). "In this study, we provide data supporting the hypothesis that the CD44v6 rather than CD44v3 acts to limit endocrine response and promote tumor progression through EGFR transactivation in breast cancer cells." (PMID 27379207, 2016). "Another work demonstrated that exosomes, small endosome-derived vesicles that are secreted by a variety of cell types and tissues, could efficiently deliver let-7a miRNA to EGFR-expressing breast cancer cells in vivo." (PMID 27187371, 2016). "LINP1 levels were correlated with EGFR expression in primary breast cancers and CCLE cell lines." (PMID 27551547, 2016). "Since PTPH1 inhibits the EGFR/Y1173 phosphorylation, we next examined if it may regulate breast cancer sensitivity to TKIs." (PMID 26079946, 2015). "Small-molecule tyrosine kinase inhibitors (TKIs) against EGFR have been evaluated in breast cancer." (PMID 25501339, 2015). "Interestingly, our data demonstrate that pre-treatment with EGFR inhibitors can sensitize breast cancer cells to DNA-damaging agents." (PMID 26036637, 2015). "Specifically, the formation of EGFR-Grb7-Ras complex enhances breast cancer cell proliferation." (PMID 26258011, 2015). "Furthermore, a more substantial elevation of PTPH1 protein-expression in breast cancer tissues appears to correlate with a significant increase in the membranous EGFR (left)." (PMID 26079946, 2015). "EGFR expression is upregulated by direct binding of HOXB7 to the EGFR promoter, while HOXB7 functions as a cofactor with ERα to cause overexpression of multiple ER-target genes, including HER2, in tamoxifen resistant breast cancer cells." (PMID 26697525, 2015). "Thus, in TNBC cells a Src Family Kinases (SFKs) influenced EGFR translocation to nucleus has been reported, which in turn enhances breast cancer cell growth." (PMID 26258011, 2015). "Given the correlation between high HER2 or EGFR expression in breast cancer cells and sensitivity to AMPK activation, we next sought to determine how AMPK activation might affect kinase activity of EGFR and HER2." (PMID 26143491, 2015). "Furthermore, there is evidence that EGFR activator proteins contribute to EGFR-dependent breast cancer cell proliferation." (PMID 26258011, 2015). "We then tested whether activation of EGFR signaling by exogenous ligand can protect HER2-amplified breast cancer cells from AICAR-induced toxicity." (PMID 26143491, 2015). "Furthermore, anti-estrogens increase ER nuclear accumulation, whereas in TAM resistant breast cancer there is increased EGFR-ER binding and extra-nucleus ER activity." (PMID 26079946, 2015).
breast carcinoma (continued). "In more recent works, EGFR protein expression was detected in 16 to 36 % of breast cancers." (PMID 26680641, 2015). "The rationale behind our hypothesis was that in breast cancer cell lines resistant to tamoxifen, a cross-talk mechanism has previously been identified between EGFR and the IGF1R signaling pathway." (PMID 25599599, 2015). "Moreover, EGFR has been identified as one of main genes conferring estrogen independence to human breast cancer cells." (PMID 26258011, 2015). "Altogether, these results strongly suggest that EGFR may be another KLF8 target important in tumor progression of breast cancer patients." (PMID 26025929, 2015). "In this report, we tested the hypothesis that PTPH1 may decrease EGFR tyrosine phosphorylation thereby regulating the ER-EGFR interaction and breast cancer sensitivity to TKIs." (PMID 26079946, 2015). "EGFR is considered to be a negative prognostic factor in breast cancer and such an association has been shown in ours, as well as in other studies." (PMID 26021752, 2015). "HER2 overexpression in breast cancer is associated with poor prognosis, but the production of HER2-targeted antibodies such as Trastuzumab (Herceptin) and Pertuzumab, and HER2/EGFR tyrosine kinase inhibitors such as Lapatinib, has revolutionized the treatment of HER2-positive breast cancer." (PMID 25865227, 2015). "Furthermore, we showed a direct correlation between high FABP5 expression and EGFR expression in breast cancer patients." (PMID 25779666, 2015). "Lapatinib is a dual EGFR/HER2 inhibitor approved by the FDA for breast cancer." (PMID 26270481, 2015). "According to these results, we propose that the antitumor activity of 5a in breast cancer cells may result from inhibition of EGFR and HER2 activity." (PMID 25766325, 2015). "Over-synthesis of MYOF in breast cancer cell lines leads to an increased invasion phenotype and secretion of matrix metalloproteinases (MMPs), while silencing of the gene restores the normal phenotype, possibly by blocking the EGFR signaling pathway." (PMID 25945082, 2015). "This is the first study demonstrating in details that RA-XII could interfere PI3K/AKT, FAK/pSRC, MAPK and EGFR signaling pathways so as to inhibit breast cancer cell invasion in vitro and RA-XII inhibited tumour growth and metastasis in vivo." (PMID 26592552, 2015). "EGFR is expressed in all types of breast cancer, especially in TNBC." (PMID 25429827, 2015). "Indeed, EBP50 can suppress EGF-induced proliferation of breast cancer cells by inhibiting EGFR phosphorylation and blocking EGFR downstream signaling." (PMID 26258011, 2015). "Furthermore, KLF4/5 protein was rapidly upregulated in human breast cancer cells following treatment with the HER2/epidermal growth factor receptor inhibitor, lapatinib." (PMID 25789974, 2015). "Additional studies are needed to investigate if PTPH1 increases the growth-inhibitory activity of TKIs in vivo and whether elevated PTPH1 in clinical breast cancer correlates with decreased p-EGFR/Y1173 levels." (PMID 26079946, 2015). "In addition, LMS causes inhibition of EGFR and COX2, which in turn, decrease lung metastatic progression in a clinically relevant model of breast cancer." (PMID 25598217, 2015). "PTPH1 also negatively regulates p-EGFR/Y1173 levels in MCF-7 breast cancer cells." (PMID 26079946, 2015). "However, results of clinical studies of EGFR-targeted therapy in breast cancer have been disappointing." (PMID 26025929, 2015). "For instance, the protooncogene EGFR, which was discovered in the eighties of the last century, was recently found to be highly expressed in a confined manner to certain cancerous tissue as in breast cancer." (PMID 25999657, 2015). "In HER2-negative breast cancer, EGFR signaling activation by Ano1 may contribute to breast cancer tumorigenesis, and thus Ano1 inhibition by tamoxifen may result in good prognosis in HER2-negative patients receiving tamoxifen treatment." (PMID 25961581, 2015).
breast carcinoma (continued). "Combining EGFR inhibitors with CD44 inhibitors may be a novel method for breast cancer treatment, especially TNBC." (PMID 25429827, 2015). "In addition, the activation of EGFR signaling in preM breast cancer is clearly of potential clinical interest." (PMID 26251034, 2015). "In this study, we used two-color, single-molecule imaging to follow the dissociation of EGFR dimers on the plasma membrane of epithelial breast cancer cells in real time and to characterize changes in the dissociation rate constant as a function of the receptor’s cytoplasmic phosphorylation state." (PMID 25762314, 2015). "Blockage of GPER/EGFR/ERK/β1-integrin signaling may be a potential target in enhancing their sensitivity for tamoxifen-resistant breast cancer patients." (PMID 25990368, 2015). "Together, EGFRvIII overexpression might decrease the sensitivity of breast cancer cells to trastuzumab via constitutively activating EGFR downstream signals including ERK, AKT, and Jak1/STAT3." (PMID 26474285, 2015). "Lastly, the reported effect is greater in MCF-7 than in MDA-MB-231 breast cancer cells, which could provide a novel basis for regulating excessive expression of EGFR in luminal cancer cells." (PMID 26493292, 2015). "Also, exposure of BT474 breast cancer cells to 25 μM genistein for 3 days reduced the expression level of EGFR, HER2 and HER3." (PMID 26694341, 2015). "In a recent study it was hypothesized that BRCA1 may down-regulate the expression of the EGFR gene by increasing the miR-146a level in breast cancer-derived cells." (PMID 26392359, 2015). "In a clinical study, constitutive presence of HER4 has been directly related with sensitivity to anti-HER2 drugs in breast cancer whereas in prostate cancer an increase of HER4 expression has been shown to be responsible of resistance to the EGFR inhibitor erlotinib." (PMID 26107737, 2015). "Furthermore, studies with breast cancer cell lines have shown that MEK inhibition also increases sensitivity to EGFR blockade, and reversed the effects of IGF-1R overexpression in promoting proliferation." (PMID 25975820, 2015). "In summary, we show evidence that activated AMPK negatively regulates HER2 and EGFR signaling by phosphorylating both of these proteins at novel regulatory sites, leading to inhibition of growth and survival of breast cancer cells that are dependent on these pathways." (PMID 26143491, 2015). "EGFR exon 19 deletions were analyzed by sizing assay in lung adenocarcinomas and breast carcinomas." (PMID 26435479, 2015). "Similarly, full sized HER2 and smaller molecular HER2 were also observed after tunicamycin treatment with varying concentrations in breast cancer cells, indicating that tunicamycin induced unglycosylated EGFR and HER2." (PMID 26498681, 2015). "Indeed, miR-146b-5p was shown to suppress EGFR expression and reduces the migration and invasion of glioma and breast cancer cells in vitro, as well as breast cancer metastasis." (PMID 26338965, 2015). "Furthermore, RA-XII was demonstrated to affect the expressions of proteins in PI3K/AKT, NF-κB, FAK/pSRC, MAPK and EGFR signaling pathways, so as to exert its anti-metastatic effects in breast cancer cells." (PMID 26592552, 2015). "Our results lead us to postulate that AMPK regulates HER2 and EGFR activity in HER2-amplified breast cancer cells and thus activation of AMPK might provide therapeutic benefit in such cancers." (PMID 26143491, 2015). "Since the ER-EGFR signal cross-talk is bidirectional, the complex formation of EGFR with ER may also play an important role in breast cancer sensitivity to TKIs." (PMID 26079946, 2015). "As EGFR and HER2 overexpression is associated with the activation of downstream PI3K/Akt and MEK/Erk pathways, we assessed the effect of 5a on these pathways in breast cancer cells." (PMID 25766325, 2015). "The close correlation between CD44 and EGFR expressions may be another reason for the resistance to EGFR inhibitors in breast cancer." (PMID 25429827, 2015).